RN7SL108P (RNA, 7SL, cytoplasmic 108, pseudogene)
Gene: Miscellaneous RNA gene on chromosome 14 (68,236,243 to 68,236,539, reverse strand). Ensembl gene ENSG00000243546.
Homologues: Orthologues: chimpanzee Metazoa_SRP (98% identical), macaque Metazoa_SRP (73% identical). Paralogues in human: RN7SL1 (80% identical), RN7SL2 (80% identical), RN7SL597P (79% identical), RN7SL3 (79% identical), RN7SL655P (79% identical), RN7SL296P (78% identical), RN7SL126P (78% identical), RN7SL709P (78% identical), RN7SL118P (78% identical), RN7SL567P (78% identical), RN7SL242P (77% identical), RN7SL448P (77% identical), and 703 more.